CD4 (CD4 molecule)
Diseases named in the same sentence as CD4 in open-access papers (continued):
Sharing a sentence is not in itself a finding about the gene and the disease.
AIDS (continued). "In contrast, from 70 to 75% of the HIV-infected CD4 T cells were conjugated by autologous CD8 T cells in acute HIV infection and AIDS patients, which are 6.5 ± 1.0 and 7.0 ± 0.9% of the CD4 T cells, respectively." (PMID 30254642, 2018). "Median values of serum TC were significantly different along sex, age, BMI, WHO clinical stages, being with ≥200 CD4+ T cells/mm3 or AIDS (<200 CD4+ T cells/mm3), being anemic/normal, and hypertriglyceridemia/normal." (PMID 29672576, 2018). "The percentage of pre-treatment AIDS events and very late presenter patients (< 200 CD4/μl) decreased passing from the first to the last period from 13 and 26% to 7 and 17%, respectively." (PMID 30005709, 2018). "We studied CD4 T cells conjugated with autologous CD8 T cells procured from the PBMC of AIDS, acute, and chronic untreated and treated HIV-infected patients as well as healthy controls." (PMID 30254642, 2018). "Progress of immunosuppression in individuals with ATLL/HTLV-1 co-infection is evidenced by an increasing HIV-1 viral loads and clinical progression of AIDS despite a stable or rising CD4 cell count." (PMID 30344845, 2018). "Factors significantly associated with undernutrition among people living with HIV/AIDS were unemployment, WHO clinical stages III/IV, CD4 count less than 350 cells/μl, tuberculosis, duration on ART, and household food insecurity." (PMID 29854730, 2018). "Reports have indicated that HIV-2 infected patients who progress to AIDS live for a longer time and have relatively higher CD4 counts compared to HIV-1 infected patients who progress to AIDS." (PMID 29416066, 2018). "More than 40% smoked, 2.2% had diabetes, the median CD4+ count was 254 cells/μL and 12.1% had a prior AIDS-defining event." (PMID 30542325, 2018). "Continued availability of ART (Anti-Retroviral Therapy) to HIV/AIDS patients, and test reagents for CD4 cell count and viral load determination are important measures to alleviate the suffering of these patients." (PMID 30558571, 2018). "In HIV-1-infected patients with low CD4+ cell count (<200/uL) and clinical AIDS symptoms, the relative abundance of bacterial phyla, e.g., Bacteriodetes, Proteobacteria, and Fusobacteria, differed from that of matched HIV-1 negative controls." (PMID 29933546, 2018). "At the time of death, they were on average 45 ± 11 years old, 45 patients died due to an AIDS‐defining illness with an average CD4+ T lymphocyte count of 199/mL (70% in C3 CDC stage), 12 of those cases being lymphomas." (PMID 30362663, 2018). "Failure to obtain a quality specimen or properly perform the CD4 assay will result in the inability to acquire a quality CD4 results for HIV/AIDS care." (PMID 30138398, 2018). "Out of these three, two were due to chronic alcoholism, and one was more in-phase C3 AIDS-related, with the count of CD4 lymphocytes being below 200 cells." (PMID 29747377, 2018). "ETR + PI exposed patients tended to have more advanced HIV disease (in terms of AIDS status and the CD4 cell count), and to have been exposed to more ARV." (PMID 29996784, 2018). "Though Markov models based on CD4 cell counts is a common approach in HIV/AIDS modelling, this paper is unique clinically in that tuberculosis (TB) co-infection is included as a covariate." (PMID 29343268, 2018). "Human immunodeficiency virus-1 (HIV-1) infection is mostly characterized by ongoing viral replication leading to a progressive decline of CD4+ T cells and eventually progression to clinical AIDS." (PMID 29490663, 2018). "In 2004, the Bond lab demonstrated that Nef interacts with CXCR4 to dispose of uninfected CD4+ T cells which likely contributes to AIDS progression in vivo." (PMID 29682200, 2018). "A decreased CD4+/CD8+ ratio, resulting from reduced CD4+, was reported in patients with acquired immune deficiency syndrome (AIDS), suggesting CD4+/CD8+ reversion was an important indicator of immunodeficiency diseases and viral infection." (PMID 29769621, 2018).
AIDS (continued). "A late diagnosis was defined as an instance in which an individual was diagnosed as having AIDS or WHO stage 3 or 4 HIV/AIDS, or had a CD4 cell count less than 200 cells/mm3 at the time of diagnosis." (PMID 29895275, 2018). "At least one study has demonstrated that VZV-specific, cell-mediated immunity is impaired in adult PLWH with a history of AIDS and low CD4 counts, which implies the importance of T-helper cells to maintaining VZV-specific, cytotoxic T-lymphocytes." (PMID 29594092, 2018). "The detection of HIV/AIDS became much cheaper with the general use of the Elisa test, which was later on followed up by more expensive testing like CD4 cell count testing." (PMID 29570687, 2018). "In our prior study, we found that blocking IFN-I during acute SIV infection in rhesus macaques resulted in reduced expression of antiviral genes, increased size of the SIV reservoir and accelerated CD4 T cell depletion and progression to AIDS." (PMID 30142226, 2018). "We studied the interaction between CD8 and CD4 T cells procured from the PBMC of AIDS, acute, and chronic untreated and treated HIV-infected patients." (PMID 30254642, 2018). "They found substantial or almost perfect agreement for age, race, and gender, but poorer agreement for mode of HIV acquisition, CD4 + cell counts, and the more complex categorization of AIDS case definition." (PMID 30514215, 2018). "44% of the patients were late presenters (LP) (presenting for care with CD4 T cells <350/mm3 or an AIDS defining event) and 24% were late presenters with advanced disease (LP-AD) (presenting for care with CD4 T cells <200/mm3 or an AIDS defining event)." (PMID 29872068, 2018). "aper 100 person‐years; adjusted for: bage, diagnosis year, 1st visit CD4; cage, current CD4, current CD4 nadir, current viral non‐suppression, time since diagnosis, previous AIDS." (PMID 30362663, 2018). "The incidence rates of composite non-AIDS endpoints were significantly different among categories with different CD4/CD8 ratio cutoff values in our study." (PMID 30261902, 2018). "According to the figure the three top most important variables for time from HIV infection to AIDS progression which were baseline CD4 cells count, age and antiretroviral therapy respectively." (PMID 30424736, 2018). "About 10∼15% of HIV-1-infected patients display a rapid decrease in CD4+ T-cell count at early stages of infection, with rapid progression to AIDS." (PMID 30619232, 2018). "A study on HIV infection provided evidence that immunomodulation by Ursodeoxycholic acid can increase the number of CD4+DPP4+ T cells in AIDS patients." (PMID 29987877, 2018). "The need to address the challenges associated with HIV/AIDS progression in the presence of TB coinfection has prompted this study and also to analyse HIV disease history based CD4 multi-states and death/loss to follow-up in a single model." (PMID 29343268, 2018). "The activated CD8+ T-cells which express HLA-DR and CD38 antigens are better indicators of AIDS and death than either CD4+ T-cell count or plasma viral load." (PMID 30034377, 2018). "A significant association was found between low CD4 counts (OR: 3.53; 95% CI: 1.55, 8.06), advanced WHO stage (OR: 6.81; 95% CI: 3.91, 11.88) and TB/ HIV/AIDS Co-infection." (PMID 30281631, 2018). "Although highly active antiretroviral therapy (HAART) has shown to increase CD4+ cell levels among HIV/AIDS patients, cryptosporidiosis still remains high in these immunocompromised individuals." (PMID 30369995, 2018). "There is a consensus that CD4 cell counts measurements have been at the core of understanding disease progression and decisions regarding initiating treatment in AIDS patients." (PMID 29487595, 2018). "As a result, people living with HIV/AIDS (PLWHA) often present with low CD4 T cell count which permits dormant human flora and other potential pathogens to revert to overt forms causing opportunistic infections and rare cancers such as Kaposi sarcoma." (PMID 29850480, 2018).
AIDS (continued). "Although therapeutic vaccinations are now aimed at a sterilizing or functional cure, initial attempts in the 1990s and early 2000s were made to therapeutically “modulate” immune responses to curb CD4 T cell decline and lower the rate of AIDS progression." (PMID 29541072, 2018). "In 2016, 8209 new cases of HIV were reported, and 34% of the newly diagnosed patients had a CD4 count of less than 200 cells/μL or AIDS-defining opportunistic illnesses, while only 25.1% had a CD4 count over 500 cells/μL." (PMID 29561795, 2018). "One consequence of HIV/AIDS among others is that the immune status of these pregnant women becomes poor due to the gradual reduction in the CD4 count." (PMID 30344800, 2018). "Furthermore, we used the AIDS prevalence to depict the dynamics of hyper-susceptible individuals in the population because indicates that about 90% of co-infected patients have CD4 cell count per μl less than 350–400 and the risk of TB increases exponentially with the decline of CD4 cell count." (PMID 30285633, 2018). "For instance, non-productively infected CD4 T cells die of pyroptosis during HIV infection accounting for the low CD4 T cell counts during AIDS." (PMID 29615985, 2018). "The overall prevalence of AIDS at presentation according to the United States CDC 2014 case definition for HIV infection (AOIs or CD4 cell count < 200 cells/μL) was 37.7% [38.5% in period 1, 38.4% in period 2, and 36.2% in period 3 (P = 0.74)]." (PMID 30055564, 2018). "Replication and destruction of CD4+ T cells, which are key effectors of the host immune response, leads to the clinical outcome of immunosuppression known as AIDS." (PMID 30481211, 2018). "The total proportion of study participants at AIDS stage with CD4+ T cell count <200 cells/mm3 or WHO clinical stages III/IV were 25.9%." (PMID 29672576, 2018). "Several other studies have also reported coinfections of these opportunistic protozoan parasites in HIV/AIDS infected individuals with lower CD4+ cells count." (PMID 30369995, 2018). "Three different specimen collection methods were evaluated for compatibility using the Alere Pima CD4 assay at 5 HIV/AIDS healthcare sites in Dar es Salaam, Tanzania." (PMID 30138398, 2018). "Children who know their status have also been shown to have slower rates of CD4% decline and lower AIDS-related mortality." (PMID 30473886, 2018). "It was shown that the baseline CD4 count is the top first important predictor of progression to AIDS." (PMID 30424736, 2018). "they further demonstrate that medication adherence is second to CD4 count for precisely anticipating progression to AIDS and death." (PMID 29879913, 2018). "Patients with lower CD4 counts, who are more likely to develop AIDS, were perhaps more sexually promiscuous, as evidenced by our findings that they had a higher number of sexual partners." (PMID 29844289, 2018). "In HIV/AIDS studies, CD4 cells are considered as a sign of disease progression in HIV-infected people." (PMID 29546067, 2018). "Of the partners with HIV infection, approximately 20% had prior AIDS-defining illness and the median nadir CD4 count was quite low, at 240 cells/mm3." (PMID 29949594, 2018). "Bw4 homozygosity has been reported to be associated with the control of HIV-1 viremia and protection against AIDS, and with a less marked decline in CD4 T-cell counts in HIV-1-infected individuals." (PMID 30147699, 2018). "Antiretroviral therapy has an impressive clinical effect in that it decreases the viral replication and viral load which in turn preserves the CD4 level, decreases the progress of AIDS, and reduces AIDS-related deaths." (PMID 29879913, 2018). "CD4+ T lymphocytes, whose mass destruction by infection facilitates the development of the main symptoms of AIDS, can also play a protective role." (PMID 29467764, 2018). "Female sex, AIDS, lower CD4, earlier year of ART initiation, and starting a regimen that did not include NNRTI were predictive of ART modification." (PMID 29569354, 2018).
AIDS (continued). "Myanmar National AIDS Program has had significant scale-up of services and changes in CD4 eligibility criterion for ART initiation from 2013 to 2016." (PMID 30252904, 2018). "CD4+ T cells are major players in the immune response against several diseases; including AIDS, leishmaniasis, tuberculosis, influenza and cancer." (PMID 30319653, 2018). "At cART initiation, in men and in women, NFW migrants had the lowest CD4 cell counts and the highest rate of AIDS, while individuals originating from France had the highest CD4 cell counts and the lowest rate of AIDS." (PMID 30379870, 2018). "Chronic diarrhea caused by opportunistic enteric pathogens is increasingly observed in HIV/AIDS patients with depleted CD4+ T lymphocytes cells in Ghana." (PMID 30369995, 2018). "HIV-specific and polyfunctional CD4+ T lymphocytes were shown to be more frequent in long-term non-progressor patients than in patients who rapidly progressed to AIDS." (PMID 29467764, 2018). "A recent working theory is that the depletion of CD4+ T cells occurs in three stages during the chronic stages of infection prior to AIDS onset such that initially effector memory (EM) T cells with high expression of CCR5 are depleted." (PMID 29259605, 2017). "CD4+/CD8+ ratio in the AIDS group was lower than OTR, NHNT-1 and NHNT-2 groups with statistical significance (median, 0.04 vs 1.39, 0.72, 1.52; P < 0.001)." (PMID 28035481, 2017). "Disseminated infection, representing 17% of extrapulmonary infections, typically occurs in severely immunocompromised patients with AIDS (CD4+ counts <50), hematologic malignancies, or transplants." (PMID 28930014, 2017). "A study of HIV patients newly clinically eligible for ART through their first reported CD4 count <350 cells or an AIDS-defining illness from the NA-ACCORD between 2001 and 2009 assessed factors associated with timely ART initiation." (PMID 28700693, 2017). "Additionally, CD4+ T cells in the skin may be essential in the immune response to scabies conferring protection as it has been seen that acquired immunodeficiency syndrome (AIDS) patients often develop CS if infected with scabies mites." (PMID 28797273, 2017). "Samples were collected from the Multicenter AIDS Cohort Study (MACS) with matched CD4 cell percentages at the first time point." (PMID 29184023, 2017). "Although the importance of CD8+ cytotoxic T cells as a first response against HIV is well established, a strong CD4+ T cell response is of utmost importance for the slow progression to AIDS." (PMID 28223987, 2017). "Using the MMP standardized sampling methodology and data collection instrument, we found disproportionate viral load suppression and normal CD4 count among people receiving care for HIV/AIDS in this state." (PMID 28387733, 2017). "Mean CD4+ T-lymphocyte count was 659 cells/mm3 (SD 273), 122 (22.9%) had a prior AIDS-defining illness, and 70 (13.4%) had hepatitis B and/or C co-infection." (PMID 28369066, 2017). "Less than half of them had more advanced HIV infection at enrolment, with 40.7% having advanced late presentation (CD4 cell count < 200 or an AIDS-defining condition in the 6 months following HIV diagnosis)." (PMID 28264665, 2017). "At enrollment, 52% of participants had a CD4 count above 500 cells/μl, and 42% of participants had a history of AIDS." (PMID 28982127, 2017). "These two macaques also had SIV plasma viral load at least 2 logs higher than IB13 and much lower CD4 counts, close to or below the 200 cells/ml cut off defining AIDS." (PMID 29259582, 2017). "Otherwise patients whose rate of CD4 regain is less than 50 cells/μl a year may possibly take a much longer time, before reaching this immunological threshold and this subgroup of patients has been shown to be at higher risk of both AIDS and non AIDS related morbidities and mortalities." (PMID 28595630, 2017).
AIDS (continued). "One recent study from Germany suggested that routine screening for cryptococcosis by testing with cryptococcal antigen (CRAG) is highly recommended for AIDS patients with CD4+ T-cell counts ≤200/μL." (PMID 28035481, 2017). "In contrast, human studies show that high MIP-1α and MCP-1 are associated with less peripheral CD4, lower CSF lymphocytes number, high risk for developing IRIS and increased mortality within AIDS patients with CM." (PMID 29333430, 2017). "We used two AIDS Indicator Surveys45, 46 to predict the age-sex-CD4 distribution of antiretroviral therapy coverage." (PMID 28919117, 2017). "A total of 34 (29%) of newly diagnosed patients had AIDS at presentation and 17% had CD4 counts of 50 cells/μL (p value 0.5)." (PMID 28744377, 2017). "For example, AIDS patients have been characterized by CD4+ T-cell depletion and inversion of the CD4+/CD8+ ratio." (PMID 28035481, 2017). "Though the number of early diagnoses has increased since 2011 in France, the number of late diagnoses has remained stable among MSM, and 25% of the estimated 6220 new HIV diagnoses in 2013 in France were still diagnosed at a late stage (<200 CD4 or AIDS)." (PMID 28222757, 2017). "AIDS-related mortality declined with increasing CD4:CD8 ratio (LR P = .005) and decreasing CD8 count (LR P = .009)." (PMID 28903507, 2017). "HIV VL is significantly higher during acute HIV infection and during late stage AIDS when the CD4 cell count is <50 cells/mm3." (PMID 28267790, 2017). "Hyponatremic patients had a lower CD4 cell count (207.5 ± 197.7/μl vs 400.4 ± 277.0/μl; P < 0.0001) and a higher prevalence of AIDS (50.3% vs 12.4%; P < 0.0001) compared to normonatremic patients." (PMID 28122494, 2017). "More than two-thirds (68.1%) of the cohort had a history of AIDS-defining illness while the median (IQR) current CD4 T-cell counts were 583 cells/uL (IQR, 427–763 cells/uL)." (PMID 29016635, 2017). "One of the most important evidence supporting the protective role of CD4+ T cells against human TB is provided by people suffering from HIV/AIDS." (PMID 28646367, 2017). "Among AIDS-related PML patients, the only identified risk factor for PML-IRIS is a lower baseline CD4 T cell count (mean 34.8 vs 71.7 for PML)." (PMID 28588577, 2017). "Recent studies have shown an increased percentage of NKG2D+CD4+ T cells in some AIDs, such as rheumatoid arthritis, Crohn’s disease and GPA13–15, indicating a possible involvement in AID pathogenesis; however, the underlying mechanism remains largely unclear." (PMID 28455530, 2017). "And mixed HCMV infection with multiple glycoprotein (gB, gO and gN) genotypes was found in 71% of HCMV infected AIDS patients with CD4 count < 100/mm3." (PMID 28467444, 2017). "Patients with F3–F4 fibrosis were more likely to have a CD4+ cell count <350/mm3, an AIDS-defining illness, and longer duration of ART and known HIV infection." (PMID 28362068, 2017). "Analyses took into consideration factors known to be associated with risk of AIDS progression, such as age at diagnosis, mode of HIV transmission, nadir CD4+T-cell count, sex and ethnicity." (PMID 28129343, 2017). "For children beyond infancy, in the presence of AIDS-defining symptoms, high VL (>100.000 copies/mL) or low CD4 levels (<25%), treatment is strongly recommended." (PMID 28443591, 2017). "The reduction of MDSCs correlated with high plasma viral loads and low CD4+ T cell counts, suggesting that depletion of BM MDSCs was associated with SIV/AIDS disease progression." (PMID 28498847, 2017). "Rhesus macaques treated with an antibody depleting CD4+ T cells before SIV infection mimic this advanced stage AIDS." (PMID 29250073, 2017). "While ART can efficiently prevent AIDS by restoring CD4+ T cell counts and suppressing viral load to undetectable levels, it fails to provide a sterilizing cure." (PMID 29250073, 2017).